NES (nestin)
Description:
Required for brain and eye development. Promotes the disassembly of phosphorylated vimentin intermediate filaments (IF) during mitosis and may play a role in the trafficking and distribution of IF proteins and other cellular factors to daughter cells during progenitor cell division. Required for survival, renewal and mitogen-stimulated proliferation of neural progenitor cells (By similarity).
Synonyms: Nbla00170; FLJ21841
Tractability: PROTAC: UniProt records ubiquitination sites on it; ubiquitination databases record sites on it; its protein half-life has been measured.
Gene: Protein-coding gene on chromosome 1 (156,668,763 to 156,677,407, reverse strand). Ensembl gene ENSG00000132688.
Subcellular location (Human Protein Atlas): Intermediate filaments
Gene Ontology:
Molecular function: protein binding; CCR5 chemokine receptor binding; intermediate filament binding
Biological process: G2/M transition of mitotic cell cycle; negative regulation of catalytic activity; negative regulation of protein binding; stem cell proliferation; brain development; central nervous system development; embryonic camera-type eye development; positive regulation of intermediate filament depolymerization; positive regulation of neural precursor cell proliferation
Cellular component: cytoplasm; intermediate filament cytoskeleton; intermediate filament
Genetic constraint (gnomAD): Loss-of-function variants: 27 observed, 29.46 expected, observed/expected ratio (o/e) 0.92, 90% interval 0.67 to 1.26. The upper end of that interval is the gene's LOEUF score, 1.26, which puts it in group 5 of 6, group 1 being the genes least tolerant of losing a copy. Missense variants: 1,867 observed, 1,947.3 expected, observed/expected ratio (o/e) 0.96, 90% interval 0.92 to 1. Synonymous variants: 822 observed, 797.97 expected, observed/expected ratio (o/e) 1.03, 90% interval 0.97 to 1.09.
Homologues: Orthologues: chimpanzee NES (99% identical), macaque NES (92% identical), pig NES (71% identical), guinea pig NES (63% identical), rabbit NES (61% identical), mouse Nes (59% identical), rat Nes (57% identical), dog NES (52% identical). Paralogues in human: NEFM (9% identical), SYNM (8% identical), NEFL (7% identical), KRT76 (7% identical), GFAP (7% identical), LMNB2 (7% identical), KRT5 (7% identical), KRT75 (7% identical), INA (7% identical), KRT8 (7% identical), PRPH (7% identical), VIM (7% identical), and 56 more.
Diseases named in the same sentence as NES in open-access papers:
NES is named in the same sentence as 358 diseases in open-access papers, as found by Europe PMC text mining. Sharing a sentence is not in itself a finding about the gene and the disease. The quoted sentences say what the papers report.
glioma (314 papers, 2006 to 2026). A benign or malignant brain and spinal cord tumor that arises from glial cells (astrocytes, oligodendrocytes, ependymal cells). "Nestin is expressed in both low-grade and high-grade gliomas, and its increased expression is associated with increased glioma malignancy, leading to poorer patient survival rates." (PMID 41141394, 2026). "On the other hand, high Nestin expression has been associated with the prognosis of patients with WHO grade II–III gliomas." (PMID 38473403, 2024). "Some studies have indicated that increased Nestin expression is associated with a poorer prognosis in glioma patients." (PMID 39598347, 2024). "The same results were observed in previous studies where Nestin expression was associated with tumor aggressiveness and poor survival rates in glioma and non-small lung cancer." (PMID 39687450, 2024). "We analyzed these cells for the expression of neural/stem precursor cell markers (OLIG1, OLIG2, CSPG4/NG2, NESTIN), which are also transcription factors and lineage markers associated with glioma stem cells (GSC), and DMRTA2." (PMID 38509074, 2024). "NES is an intermediate filament protein associated with neural stem cells during brain development, encoded by the gene NES, and associated with histologic grade of gliomas." (PMID 36333778, 2022). "Some studies suggested that Nestin expression is linked to a higher grade and worsens prognosis in gliomas." (PMID 32429463, 2020). "Increase in Nestin expression has been correlated with increasing glioma grade while loss of Nestin expression has been shown to impair cell growth, stem cell marker expression and impair tumorigenic ability." (PMID 31491006, 2019). "In contrast, when an Egfr activating mutation was introduced in the presence of Cdkn2a loss, gliomas arose at a high frequency particularly on the nestin-TVA (Ntv) background." (PMID 31505839, 2019). "For nestin, too, inducible upregulation is associated with a number of neurological diseases, including gliomas and astrocytomas." (PMID 31126068, 2019). "Additional western blot analysis indicates that ATM knockout also caused significantly reduced expression of Oct4 and Nestin, two important markers of glioma stem cells." (PMID 28337983, 2017). "As the markers of cancer stem cells, CD133 and nestin are also associated with the prognosis of glioma patients." (PMID 28641579, 2017). "Nestin is a protein marker for neural stem cells and glioma stem cells and is associated with poor clinicopathological features and prognosis in glioma patients." (PMID 29234033, 2017). "For instance, the association of coexpression of Nestin/CD133 is helpful in predicting the aggressive nature of gliomas." (PMID 26977157, 2016). "In this study, we aimed to evaluate the association between the expression of CD133 and Nestin and the outcome of glioma patients by conducting a systematic review and meta-analysis." (PMID 25967234, 2015). "Thirty two studies were included in those studies including 19 studies investigated the association between CD133 expression and outcome of glioma patients and 13 studies for Nestin." (PMID 25967234, 2015). "For example, oncolytic HSV rQNestin34.5 is transcriptionally silenced upon infection of glioma cells, due to increased DNA methylation levels at the virally encoded mammalian Nestin promoter." (PMID 25101247, 2014).
glioma (continued). "Since various stem cell markers have been associated with a tumorigenic phenotype in human gliomas, we analyzed invasive and angiogenic xenografts for the expression of the stem cell markers nestin, sox2 and CD133." (PMID 23429996, 2013). "In order to gain insight into the identity nestin-positive cells attracted by glioma, we studied the morphology of tumor-associated host cells after immunofluorescent double-labeling of human and rat nestin in tissue from the biopsy xenograft model." (PMID 22539956, 2012). "Enhanced levels of transcripts encoding Sox2, Musashi 1, Nestin and Vimentin were observed in the glioma cultures assayed and in neural stem cells as compared to adult cortical tissues." (PMID 21297991, 2011). "In our study we used PDGF-B driven PTEN-deficient and PTEN-intact mouse gliomas generated in nestin-tv-a/ink4a-arf-/-/ptenfl/fl mice." (PMID 21267448, 2011). "In addition, Sohlh1 was positively correlated with the expression of SFRP1, whereas negatively associated with the expression of Nestin in glioma tissues, suggesting a tumour suppressive role in the stemness of glioma." (PMID 40418209, 2025). "This may be explained by differential losing or gaining of nestin expression, as literature shows that subpopulations of glioma cells can differ in their mutational status." (PMID 40414994, 2025). "Furthermore, a nestin down-regulation is associated with an increased adhesion to collagen, fibronectin, and laminin, leading to an inhibition of migration of glioma cells, while overexpression had the reverse effect." (PMID 31003495, 2019). "In the present study, the effects of melatonin on the transcriptional regulation of three genes associated with cell proliferation (Nestin, Bmi-1 and Sox2), and on C6 glioma cell survival and viability, were investigated in vitro to evaluate the use of melatonin in cancer therapy." (PMID 24137328, 2013). "For example, in this context, nestin expression may potentially serve as a biologic marker for a high-risk low-grade glioma, which could have a direct clinical application." (PMID 18817556, 2008). "An association between increased Nestin expression and gliomas of a higher grade could be shown." (PMID 35183162, 2022). "Therefore, we asked whether nestin+ cells in lower-grade IDH1mut gliomas were linked to PpIX fluorescence." (PMID 33959713, 2021). "In GSC xenograft models, both proliferating cell nuclear antigen (PCNA) and Nestin expression are positive, with Nestin levels showing a positive correlation with the degree of differentiation, malignancy, migration, and invasion of glioma cells." (PMID 41141394, 2026). "SUV39H1 expression was positively correlated with the classic-like glioma subtype and markers such as NES and EGFR, with a lower correlation with mesenchymal-like markers like CD44 and CHI3L1." (PMID 40059829, 2025). "CAN-3110 (linoserpaturev) is a replication-competent oHSV under the control of a nestin promoter, designed to confine viral replication to nestin-positive glioma cells." (PMID 41463198, 2025). "Lv reported that the expression of Nestin in high‐grade gliomas was significantly greater than that in low‐grade gliomas." (PMID 40936205, 2025). "AGR2’s co-expression with stemness markers such as Nestin and Vimentin highlights its role in maintaining glioma stem cell survival and contributing to recurrence, positioning AGR2 as a potential diagnostic and therapeutic target." (PMID 41179304, 2025). "Studies have shown that peptides can bind to the N-terminal isoform of nestin specifically expressed in glioma stem cells, a property that enables them to target nestin-positive cell populations in human glioma tissues." (PMID 40799240, 2025).
glioma (continued). "Our findings of ATRA-induced downregulation of SOX2 and Nestin mRNA are broadly consistent with previous reports indicating ATRA can induce differentiation in various glioma cell line models." (PMID 40422249, 2025). "Expression of Nestin, a progenitor cell marker, correlates with the grade of glioma malignancy and is involved in the regulation of their growth, migration, and invasive potential." (PMID 41304780, 2025). "Several genes included in our signature, notably NOTCH1, NES, E2F1 and EGFR, have been implicated in glioma adaptation to temozolomide (TMZ) therapy, where changes in their expression or activity influence stemness, invasion and drug resistance." (PMID 41375052, 2025). "We have previously confirmed the presence of glioma stem-like cells, cells expressed neural stem cell markers, nestin and vimentin which are regarded as tumorigenic and associated with the heterogeneity in GBM." (PMID 40569470, 2025). "High Nestin expression can also be used to distinguish glioma cells from unaffected brain tissue with a high probability." (PMID 39039193, 2024). "For example, in the p16Ink4a knockout RCAS PDGFB/Nestin-tvA glioma mouse model, the downregulation of PTPRD promoted cell proliferation, whereas restoring PTPRD expression in GBM cells resulted in the suppression of cell growth and the induction of apoptosis." (PMID 38339334, 2024). "Several studies have suggested that a high percentage of Nestin-positive cells correlates with aggressiveness and poor prognosis; however, such observations are found in homogenous glioma cell lines." (PMID 38256907, 2024). "Using glioma cell cultures, we noted increased Nestin expression only in the surviving tumor cells of recurrent tumors, whereas primary tumors had no such change after exposure to the aptamer." (PMID 38256907, 2024). "The Nestin promoter drives selective replication in glioma cells, enhancing glioma suppression when combined with cyclophosphamide." (PMID 39906660, 2024). "Nestin is widely recognized as a neuroepithelial stem cell marker and is frequently upregulated in gliomas, with its expression increasing in correlation with the degree of malignancy." (PMID 39598347, 2024). "Another study also showed that circPTN promotes glioma growth and stemness by sponging miR-145-5p and miR-330-5p, this results in increased expression of NES, CD133, SOX9 and SOX2, which promotes self-renewal of glioma stem cells and regulates gliomagenesis." (PMID 39698112, 2024). "The CSCs of paediatric high-grade gliomas were isolated as early as 2003, with stemness markers of Nestin and Musashi, along with the differentiation markers of Beta-III Tubulin, GFAP, and Oligodendrocyte Marker O4." (PMID 37370764, 2023). "Because the glioma stem cell niche is associated with overexpression of several proteins, including OCT4, Nestin, Vimentin, and Sox-2, we sought to visualize HML-2 expression in situ with multiplex immunofluorescence." (PMID 37395282, 2023). "We found HML-2 expression in the same cells and tissues that expressed stem cell markers, namely OCT4, Nestin, Vimentin, and Sox2 in patients with high-grade glioma." (PMID 37395282, 2023). "In GBM, the proteins Sox2, CD133, SSEA1, CD49f, Musashi-1, and Nestin are considered to be glioma stem cell CSC markers." (PMID 36900417, 2023). "For instance oncolytic herpes viruses have been developed for selective replication in glioma cells using the nestin promoter to control the virulence gene ICP 34.536." (PMID 37236967, 2023). "Consistently, we found that IDHmt glioma cells contained significantly less Filipin+/Nestin+ volumes than IDHwt counterparts, indicating a reduced intracellular cholesterol level in IDHmt tumor parenchyma (IDHwt: IDHmt = 0.52: 0.19, p = 0.0012)." (PMID 37166058, 2023). "NES is an example of a gene that elucidates the Glioma-BioDP webtool’s ability to identify genes that have a significant effect on prognosis in LGG but not GBM." (PMID 37454191, 2023).
glioma (continued). "As nestin is overexpressed in a variety of neoplasms, including glioma, this neurovirulence gene expression should be limited to nestin expressing neoplasms." (PMID 37375742, 2023). "Further, RREB1 can directly regulate NESTIN gene expression which plays an important role as a glioma stem cell biomarker in maintaining glioma stemness." (PMID 36635261, 2023). "The expression profiles of CD133, CD44, Nestin, SOX2, Nanog, ALDH1A3 and OCT4, which are associated with glioma stem cell (GSC) signatures, were visualized in a heatmap." (PMID 36755314, 2023). "The intramural infusion rQNestin is engineered for enhanced replication in glioma, with a γ134.5 copy reinserted into G207 under a synthetic nestin promotor, selectively expressed in actively mitotic cells." (PMID 37568717, 2023). "Grown in the presenceof FGF2 on fibronectin-coated plates and in N2 medium with supplements,C6 glioma cells grown as NSPCs (referred to as C6DCs) formed uniformcultures of nestin-positive cells." (PMID 37647213, 2023). "Then, we quantified the expression of lncRNA FOXD2‐AS1, TATA‐box binding protein associated factor 1 (TAF‐1) and NOTCH1 in glioma tissues and GSCs, as well as the expression of GSC stem markers, OCT4, SOX2, Nanog, Nestin and CD133 in GSCs." (PMID 35419917, 2022). "Several known glioma markers were identified through this analysis such as Vimentin, Nestin, BCAT1, and S100A1." (PMID 35526077, 2022). "In particular, the panel included extracellular and intracellular antigens expressed on normal brain and tumor cells (e.g. GFAP, CD140α, CD90), stem cells and glioma cancer stem cells (e.g. Nestin, Musashi-1, CD34)." (PMID 36568177, 2022). "For example, in glioma, Nestin positive cells labeled with stem cell like populations enable tumor cells to survive and proliferate when exposed to chemotherapeutic drugs." (PMID 35444938, 2022). "CD133, Nestin and SOX2 expression were positively associated with ITGB8 expression in TCGA and Chinese Glioma Genome Atlas (CGGA) databases, and we further confirmed that ITGB8 was closely correlated with Nestin expression in GBM specimens." (PMID 35676251, 2022). "Eventually, nestin-positive TM network–integrated glioma cells account for the vast majority of the tumor cells after radiotherapy." (PMID 35847909, 2022). "Recurrent loss or other inactivation of PTPRD has been detected in different human malignancies, and one-copy loss of PTPRD has also been oncogenic in p16Ink4a knockout RCAS PDGFB/Nestin-tvA glioma mouse model." (PMID 35982066, 2022). "The expression of the neural stem cell markers Nestin and Sox2 are consistent with the features of most drug-resistant glioma stem cell populations and support the neural stem cell lineage of GBM." (PMID 36316307, 2022). "In glioma cell cultures, silencing of uPAR and cathepsin B downregulates the expression of CD133, Nestin, Sox2 and Bmi1 and reduces the number of glioma-initiating cells." (PMID 35493073, 2022). "Nestin is known to be one of the best-established markers of cell stemness and treatment resistance in gliomas." (PMID 35847909, 2022). "These were immunohistochemically double stained with antibodies against the proliferation-associated antigen Ki67 and marker proteins for glioma stem cells (CD133, Nestin, Musashi, CD15, CD44), and differentiated glioma cells (GFAP, MAP2c)." (PMID 34170383, 2021). "As expected, reduced NUPR1 and increased Nestin expression were observed in 3D collagen/FN cultured glioma cells, whereas blockade of integrin αvβ3 or CDC42 overexpression reversed the phenomenon." (PMID 33408794, 2021). "Infiltrating Treg cells in glioma upregulate the expression of the core stem cell markers CD133, SOX2 and NESTIN in glioma stem cells, which are enriched by TGF-β secretion." (PMID 34202411, 2021). "Considering that nestin + and FGFR1 + are the phenotypes of glioma CSCs, we believe that the CSC-subpopulation of glioma cells is likely less susceptible to Tf@pSiNPs." (PMID 33637089, 2021).